Y_RNA (Y RNA )
Gene: Miscellaneous RNA gene on chromosome 2 (140,992,543 to 140,992,659, forward strand). Ensembl gene ENSG00000201892.
Homologues: Orthologues: chimpanzee Y_RNA (100% identical). Paralogues in human: Y_RNA (79% identical), RNY1 (79% identical), Y_RNA (78% identical), Y_RNA (77% identical), RNY1P10 (76% identical), RNY1P11 (76% identical), Y_RNA (76% identical), Y_RNA (75% identical), Y_RNA (74% identical), RNY1P12 (74% identical), RNY1P8 (74% identical), RNY1P5 (73% identical), and 92 more.